IGFBP5 (insulin like growth factor binding protein 5)
Diseases named in the same sentence as IGFBP5 in open-access papers (continued):
Sharing a sentence is not in itself a finding about the gene and the disease.
osteosarcoma (26 papers, 2010 to 2025). A usually aggressive malignant bone-forming mesenchymal neoplasm, predominantly affecting adolescents and young adults. "Strikingly, an NLS-mutated version of IGFBP5 is able to fully support the IGF-induced anti-apoptotic effect on osteosarcoma cells, suggesting that the nuclear effects of IGFBP5 are independent of the IGF-depending ones." (PMID 36093095, 2022). "IGFBP5 inhibits cell proliferation, migration, and invasion in vitro indicating that it is anti-tumorigenic in osteosarcoma." (PMID 36465383, 2022). "IGFBP5 has been suggested to act as a tumor suppressor in several cancers including ovarian cancer, melanoma, and osteosarcoma." (PMID 36465383, 2022). "IGFBP5 additionally suppressed tumor growth and metastasis in several models of osteosarcoma and melanoma." (PMID 36465383, 2022). "The splicing variant WT1(-KTS), which misses this sequence, was found to bind to and activate the IGFBP5 promoter in osteosarcoma cells." (PMID 36093095, 2022). "Our group previously used adenovirus to induce IGFBP5 overexpression in osteosarcoma cells and confirmed that IGFBP5 can induce apoptosis and inhibit invasion, migration and proliferation of osteosarcoma cells." (PMID 33614075, 2021). "IGFBP-5 levels are significantly elevated in osteosarcoma cells that exhibit high metastatic potential." (PMID 32194505, 2020). "IGFBP-5 was first identified and purified from human bone extracts and conditioned media collected from cultured human osteosarcoma cells." (PMID 32194505, 2020). "And overexpression of IGFBP5 inhibits cell proliferation in human osteosarcoma cell lines and human melanoma cell line." (PMID 32127912, 2020). "In contrast, in osteosarcoma cells, endogenous and exogenous IGFBP-5 have been shown to exert opposite effects." (PMID 30374330, 2018). "IGFBP5 is the most conserved member of the IGFBPs family and is frequently deregulated in human malignancies such as neuroblastoma, osteosarcoma, breast as well as head and neck squamous cell carcinoma." (PMID 27893412, 2017). "IGFBP5 has been identified as a hub gene in osteosarcoma along with origin recognition complex subunit 6 (ORC6), minichromosome maintenance 10 replication initiation factor (MCM10), MET proto-oncogene, receptor tyrosine kinase (MET) and centromere protein F (CENPF)." (PMID 36465383, 2022). "Increased expression of miR-140 could modulate cancer cell chemoresistance by targeting IGFBP-5 and sensitizes osteosarcoma cells to chemotherapy by promoting HMGN5-mediated autophagy." (PMID 34479600, 2021). "Moreover, IGF-1 and/or IGFBP-5 participate in the estrogen-mediated regulation of PTH action on Saos2 osteosarcoma cell proliferation and collagen I production." (PMID 34069554, 2021). "In this study, SPCIONPs were prepared to load the IGFBP5 plasmids, which could inhibit lung metastasis of osteosarcoma." (PMID 33614075, 2021). "Indeed, 7–14% of osteosarcoma cases exhibit mutations in IGF signaling genes (IGF1R, IGF1, IGF2R, and IGFBP5)." (PMID 34069554, 2021). "They found that knockdown of IGFBP-5 increased osteosarcoma cell apoptosis." (PMID 32194505, 2020). "Likewise, stable overexpression of IGFBP-5 was found to inhibit mouse osteosarcoma cell proliferation." (PMID 32194505, 2020). "The association of IGFBP-5 with four and a half LIM domain protein within the nucleus of U2 osteosarcoma cells has also been reported although the functional significance of this observation remains unknown." (PMID 29503631, 2018). "The notion that the N- and C-terminal domains of IGFBP5 have different functions is also supported by a study that showed that the N-terminal domain blocks proliferation of osteosarcoma cells and induces apoptosis, whereas the C-terminal domain inhibits migration and invasion." (PMID 26515727, 2015). "Previous work in our laboratory has demonstrated that RASSF1C binds to IGFBP-5 and may regulate osteosarcoma cell proliferation and apoptosis." (PMID 25007054, 2014).
osteosarcoma (continued). "Also, IGFBP5 enhances the anti-apoptotic effect of IGF on osteosarcoma cells." (PMID 36093095, 2022). "Moreover, different IGFBP-5 fragments might have different activities in osteosarcoma cells: while the N-terminal domain fragment inhibited cell proliferation and induced apoptosis, its C-terminal domain inhibited cell migration and metastases." (PMID 32194505, 2020). "However, others found that IGFBP-5 expression inhibited osteosarcoma tumor growth and metastasis." (PMID 32194505, 2020). "qRT-PCR showed MYC, BNIP3, IGFBP5, and SPP1 substantially exhibited a trend of high expression in osteosarcoma cells." (PMID 41282023, 2025). "The introduction of the siRNA-resistant IGFBP-5 into IGFBP-5 knocked down cells rescued cells from apoptosis, suggesting that IGFBP-5 is both required and sufficient for maintaining osteosarcoma cell survival." (PMID 32194505, 2020). "IGFBP-5 is the most abundant IGFBP in bone tissues and there is a host of in vitro findings in the literature regarding IGFBP-5 actions in osteosarcoma cells." (PMID 32194505, 2020). "Studies have identified genes which specifically suppress in vitro migration and invasion of osteosarcomas, including LRP5 and IGFBP5." (PMID 23767896, 2013). "We have recently identified RASSF1C as an Insulin-like Growth Factor Binding Protein-5 (IGFBP-5) interacting protein and have shown that silencing of RASSF1C expression resulted in a significant decrease in osteosarcoma and lung cancer cell proliferation." (PMID 20955597, 2010). "Despite the lack of prognostic significance, IGFBP5 was shown to play an important role in osteosarcoma using several in vivo models." (PMID 36465383, 2022). "Furthermore, it has been shown that IGFBP5, the most profuse bone IGFBP stored in bone, attenuates tumor growth and human osteosarcoma metastasis." (PMID 34069554, 2021). "IGFBP5 primarily binds to insulin growth factors to inhibit the IGF1 and IGF2 signalling pathways, thereby inhibiting the proliferation, migration and invasion of osteosarcoma, and is a key inhibitor of in situ osteosarcoma growth and lung metastasis." (PMID 33614075, 2021). "The introduction of NLS::GFP but not LBD::GFP into IGFBP-5 knocked down human osteosarcoma cells rescued them from apoptosis." (PMID 32194505, 2020).
pulmonary fibrosis (26 papers, 2008 to 2025). Chronic progressive interstitial lung disorder characterized by the replacement of the lung tissue by connective tissue, leading to progressive dyspnea, respiratory failure, or right heart failure. "IGFBP-5, in particular, has been implicated in promoting pulmonary fibrosis through increased collagen and fibronectin expression and induction of fibroblast/myoblast transdifferentiation independent of IGF-I (85, 87‐89)." (PMID 39418083, 2025). "We recently reported that IGFBP-5 levels were significantly increased in lung tissues and primary pulmonary fibroblasts of patients with SSc-associated pulmonary fibrosis." (PMID 33396956, 2020). "We also reported that IGFBP-5 levels were significantly increased in lung tissues and primary pulmonary fibroblasts of patients with SSc-associated pulmonary fibrosis." (PMID 33396956, 2020). "In particular, IGFBP5 plays a causal role in the induction of cellular senescence and inflammation, which may be linked to pulmonary fibrosis." (PMID 33823868, 2021). "IGFBP5 is upregulated in idiopathic pulmonary fibrosis (IPF) and contributes to fibroblast activation and ECM remodeling." (PMID 40144669, 2025). "Insulin-like growth factor binding protein 5 (IGFBP5) was reported as a pro-fibrotic factor in pulmonary fibrosis." (PMID 36726784, 2022). "In bleomycin-induced pulmonary fibrosis, in our study model, expression of endogenous mouse Igfbp-5 was downregulated." (PMID 33396956, 2020). "Our results demonstrate that the increase in IGFBP-5 levels is a primary and early event in pulmonary fibrosis since IGFBP-5 induces expression of ECM and pro-fibrotic genes as early as 1 h post-stimulation." (PMID 30374330, 2018). "We propose that IGFBP-5 promotes pulmonary fibrosis by directly inducing expression of ECM genes and by increasing levels of other pro-fibrotic proteins such as CTGF, resulting in further increase of ECM production." (PMID 30374330, 2018). "IGF-1 and IGFBP-5 expressions are significantly reduced in ATII cells in a rat model of bleomycin-induced pulmonary fibrosis." (PMID 30018981, 2018). "Finally, in vivo overexpression of IGFBP5, using replication-deficient adenovirus, induced skin fibrosis in mice which included increased thickness of the dermis and increased collagen bundle thickness and induced pulmonary fibrosis with myofibroblastic changes." (PMID 21637366, 2011). "We have previously shown that IGFBP-5 is over-expressed in fibrotic lung and skin tissues in patients with SSc and in lung tissues of patients with idiopathic pulmonary fibrosis." (PMID 19088866, 2008). "We have also demonstrated that IGFBP-5 can induce the development of a fibrotic phenotype in vitro in primary fibroblasts and can trigger dermal and pulmonary fibrosis in vivo in murine models." (PMID 19088866, 2008). "Furthermore, the expression of IGFBP-5 is increased in bleomycin-induced pulmonary fibrosis in rats." (PMID 30374330, 2018). "IGFBP5 (insulin‐like growth factor‐binding protein 5) is also one of the substantially upregulated genes in D (82‐fold, compared to N), and it has been observed to be upregulated in the fibrotic disorders systemic sclerosis/scleroderma and idiopathic pulmonary fibrosis." (PMID 31134759, 2019). "Additionally, IGFBP-5 has been shown to induce EC senescence and lung fibrosis through EGR-113." (PMID 27752126, 2016). "Although IGFBP-3 and IGFBP-5 are able to bind IGF, it is possible that they also have IGF-independent roles in pulmonary fibrosis." (PMID 39418083, 2025). "Previous studies have shown that IGFBP5 is involved in the development of lung diseases such as COPD and pulmonary fibrosis by regulating cellular inflammation and oxidative stress, which are also key pathological features of PM-induced lung injury." (PMID 40672360, 2025).
pulmonary fibrosis (continued). "We selected the Insulin-Like Growth Factor Binding Protein 5 (IGFBP5, FoldChange = 24.8 and p < 0.01), which is a biomarker of pulmonary fibrosis and is also involved in stimulating the growth of intestinal smooth muscle and collagen synthesis." (PMID 37393249, 2023). "IGFBP-5 was shown to be upregulated in lung tissue from patients with idiopathic pulmonary fibrosis (IPF), and exogenous IGFBP-5 also stimulates the secretion of ECM components by IPF lung fibroblasts." (PMID 32194505, 2020). "Findings with IGFBP2 are consistent with our previous studies showing increased expression of IGFBP3 and IGFBP5 in IPF and SSc-PF and reinforced the crucial role that IGFBPs and the IGF pathway play in the development and perpetuation of pulmonary fibrosis." (PMID 32210969, 2020). "In a mouse model of lung fibrosis, IGFBP5 induced migration of activated CD4+T cells and monocytes, indicating a chemoattractant activity of IGFBP5 for immune cells." (PMID 30214426, 2018). "In a mice model of bleomycin-induced pulmonary fibrosis, three miRNAs and IGFBP3 are decreased, while IGF-1, IGFBP-5, and 8 miRNAs are increased." (PMID 30018981, 2018). "Curiously, IGFBP5 has a relatively well-documented role in pulmonary fibrosis but not in fibrogenesis of other major organs (e.g., the liver)." (PMID 38092723, 2023). "Several studies of idiopathic pulmonary fibrosis (IPF) and rheumatoid arthritis suggested a correlation between IGFBP5 and TGF-β in fibrosis and autoimmune disease, but the precise interaction between IGFBP5 and TGF-β is still unclear." (PMID 31886201, 2019). "Thus, in vitro and in vivo experiments are needed to confirm whether IL-17-producing cells are the targets of HGF and whether IGFBP5 and SCRG1 participate in the treatment of pulmonary fibrosis." (PMID 36726784, 2022). "In Idiopathic Pulmonary Fibrosis (IPF), one of the common interstitial lung diseases, Hsp70s were observed to be downregulated in response to an increase in the profibrotic molecules, IGFBP5 (insulin-like growth factor-binding protein 5) or (TGF β1) transforming growth factor-β1." (PMID 36032680, 2022). "Over expression of Insulin like Growth Factor Binding Protein 5 (IGFBP-5) has been correlated with cellular senescence and also identified as profibrotic factor which could be an important target for antifibrotic therapies in the case of Idiopathic Pulmonary Fibrosis." (PMID 33343356, 2020).
melanoma (23 papers, 2013 to 2025). A malignant, usually aggressive tumor composed of atypical, neoplastic melanocytes. "It has been reported that KMT2D loss directly decreases the expression of PER2 or IGFBP5 in lung cancer and melanoma respectively, which leads to the subsequent increased glycolysis." (PMID 39117659, 2024). "DIRC3 therefore possesses IGFBP5–dependent gene regulatory functions in melanoma that act to control cancer associated biological processes." (PMID 31881017, 2019). "However, the function and underlying mechanism of IGFBP5 in tumor growth and metastasis has been elusive, particularly in malignant human melanoma." (PMID 26010068, 2015). "Indeed, our results show that IGFBP5 depletion phenocopies the increased anchorage-independent growth effect of DIRC3 loss in SK-MEL-28 cells whilst others have reported that IGFBP5 overexpression reduces anchorage-independent growth in A375 melanoma cells." (PMID 31881017, 2019). "Both KMT2D and IGFBP5 act as tumor suppressors in melanoma cells and, in metastatic melanoma, the IGFBP5 level correlates with that of KMT2D." (PMID 36093095, 2022). "Overexpression of IGFBP5 in A375, a malignant melanoma cell line, dramatically reduced tumor size in a subcutaneous xenograft model and reduced tumor growth and metastasis in a pulmonary metastasis model." (PMID 36465383, 2022). "The resulting IGFBP-5 downregulation enhanced anchorage-independent growth of melanoma cell lines, the proposed mechanism being enhanced IGF1R signaling, although this was not demonstrated." (PMID 35597813, 2022). "IGFBP5 suppresses pathogenesis and metastasis of malignant melanoma through inhibition of ERK1/2 and P38-MAPK pathways." (PMID 36465383, 2022). "Together, these data indicate that DIRC3 is a nuclear localised transcriptional regulator that acts in cis in a transcript-dependent manner to activate expression of the adjacent IGFBP5 tumour suppressor gene in melanoma." (PMID 31881017, 2019). "Although, TAD structures can vary between normal tissues and cancers, a high proportion of TADs are invariable and we found that DIRC3 levels positively correlate with IGFBP5 in TCGA melanoma RNA-seq samples." (PMID 31881017, 2019). "Overexpression of the IGFBP5 mediator of insulin-like growth factor receptor (IGF1R) signalling inhibits the transformation of human melanoma cells in culture whilst TNS1 expression is down-regulated in multiple cancers including melanoma." (PMID 31881017, 2019). "Given the key role of IGFBP5 in melanoma biology, its regulation by DIRC3 downstream from MITF-SOX10 is likely significant." (PMID 31881017, 2019). "Taken together, these results define DIRC3 as a new melanoma tumour suppressor gene that acts through IGFBP5 to inhibit the anchorage-independent growth of melanoma cells in culture." (PMID 31881017, 2019). "In contrast, IGFBP5 acts as tumor suppressor in melanoma through attenuation of stem-like cell activity." (PMID 28137308, 2017). "Recent study also supports that insulin-like growth factor binding protein 5 (IGFBP5) acts as a tumor suppressor in human melanoma by inhibiting EMT phenotype and attenuates the expression of stem cell markers such as Nanog, Sox2, Oct4, KLF4 and CD133." (PMID 28137308, 2017). "To investigate the role of IGFBP5 in melanoma progression, we stably transfected the human melanoma cell line A375 with IGFBP5, which enabling high expression of IGFBP5, as shown with western blot (WB) and qRT-PCR (panels A1 and A2)." (PMID 26010068, 2015). "In other recent studies the tumor suppressant role of IGFBP-5 has been shown in melanoma cells, osteosarcoma and ovarian cancer cells." (PMID 26569312, 2015). "In clinical samples, the expression of IGFBP5 in melanoma samples (n = 10) is higher than in normal pigmented nevus samples (n = 5) significantly by qRT-PCR analysis (*, p < 0.05)." (PMID 26010068, 2015).